LINC03085 (long independently transcribed non-coding RNA 3085)
Synonyms: AC073534.2
Gene: Long non-coding RNA gene on chromosome 19 (24,146,701 to 24,147,081, forward strand). Ensembl gene ENSG00000276030.
Diseases named in the same sentence as LINC03085 in open-access papers:
LINC03085 is named in the same sentence as 1 disease in open-access papers, as found by Europe PMC text mining. Sharing a sentence is not in itself a finding about the gene and the disease.
LINC03085 shares sentences with these, for which no sentence is quoted: acute myeloid leukemia (1 paper).